IL10 (interleukin 10)
Diseases named in the same sentence as IL10 in open-access papers (continued):
Sharing a sentence is not in itself a finding about the gene and the disease.
skin infection (13 papers, 2013 to 2025). An inflammatory process affecting the skin, caused by bacteria, viruses, parasites, or fungi. "A recent study using a murine model of repeated exposures to schistosome cercariae prior to the onset of chronic egg deposition, revealed that the skin infection site becomes rich in Th2-associated IL-4, but also immune regulatory IL-10." (PMID 25974019, 2015). "We showed previously that after repeated infection, M2-like dermal APCs conditioned within the skin infection site, which is rich in IL-4 and IL-10, were associated with decreased CD4+ T cell responsiveness in the skin draining lymph node." (PMID 25974019, 2015). "Similarly in a localized skin infection model S. aureus promotes the expansion of MDSCs leading to the upregulation of IL-10 production, which was associated with the persistence of the bacteria within the skin." (PMID 32425944, 2020). "During both nasal colonization and skin infection, S. aureus drives local production of the immunosuppressive cytokine IL-10 as a means of dampening effector T cell responses, thereby facilitating bacterial persistence." (PMID 38973612, 2024). "The use of a novel TLR2/STING agonist adjuvant was shown to be particularly effective for targeting S. aureus skin infection and, furthermore, can be improved by the inhibition of IL-10." (PMID 38973612, 2024). "For the first time to our knowledge, we show that blockade of IL-10 during vaccination can improve protection against both systemic and local skin infection with S. aureus." (PMID 38973612, 2024). "In contrast to acute systemic infections, where IL-10 production typically benefits the host by mitigating against excessive inflammation and immunopathology, IL-10 facilitates SA persistence role during acute localized skin infection." (PMID 38786139, 2024). "In mouse models of peripheral infection, IL-10 was critical for promoting S. aureus skin infection where IL-10 KO mice had lower bacterial burden concomitant with increased phagocyte, ɣδ T cell, and CD4+ T cell recruitment." (PMID 37179295, 2023). "In addition, it reduced the bacterial load and regulated the levels of inflammatory cytokines IL-6 and IL-10 at the wound site in a mouse skin infection model." (PMID 40572502, 2025). "Here, using a murine model of repeated infection with Schistosoma mansoni larvae, we show that the skin infection site becomes rich in regulatory IL-10, whilst in its absence, inflammation, neutrophil recruitment, and local lymphocyte proliferation is increased." (PMID 25974019, 2015). "It has previously been shown that S. aureus can induce IL-10 production in a skin infection model to promote its persistence by inhibiting effector T cells, suggesting that a similar mechanism may occur during S. aureus infection and/or colonization of the respiratory tract." (PMID 32425944, 2020). "Using a murine model, repeated infections result in IL‐10‐dependent CD4+ T‐cell hyporesponsiveness in the skin‐draining lymph nodes (sdLN), which could be caused by an abundance of eosinophils and connective tissue mast cells at the skin infection site." (PMID 26679416, 2016). "The reduced IL-10 levels could be allowing amplified NLRP3 activation and IL-1β production during S. aureus skin infection." (PMID 38973612, 2024). "Levels of the proinflammatory cytokines IL-1, IL-6, and TNF-α were elevated during wound healing, consistent with previously reported results showing elevated IL-1, IL-6, IL-10, TNF-α, IL-2, IL-8, IL-13 and granulocyte colony-stimulating factor (G-CSF) in the skin infection wound model." (PMID 36901790, 2023).
thyroid cancer (13 papers, 2015 to 2025). "Moreover, the study focused on the serum interleukins has shown that high serum IL-10 level was positively associated with an increased risk of thyroid cancer, but it was significant only in women." (PMID 32655554, 2020). "One previous study reported that 20 thyroid cancer patients had significantly higher IL-10 levels than 50 healthy individuals." (PMID 40150133, 2025). "Recently, it has been found that PD-1+Breg is abundant in thyroid cancer tissue and peripheral blood, and inhibits T cell viability and proliferation in an IL-10-independent manner." (PMID 38953025, 2024). "Tregs (CD4+CD25hiCD127lo) inhibit the anti-tumor response by producing IL-10 and expressing immune checkpoints CTLA-4 and PD-1, hence higher number of these cells in the circulation is associated with more aggressive thyroid cancer." (PMID 38235146, 2023). "The most frequently associated genes with thyroid cancer found on PubMed were BAX, XRCC1, XRCC3, XPO5, IL-10, BRAF, RET, and K-RAS." (PMID 37211566, 2023). "IL-4 and IL-10 protect thyroid cancer cells from cytotoxic effect of antineoplastic drugs by induce the expression of Bcl-xL and Bcl-2." (PMID 32655554, 2020). "IL4 and IL-10 plays significantly role in protecting thyroid cancer cells from apoptosis when complicated with Graves' disease." (PMID 32655554, 2020). "Another study also reported that higher levels of positive expression of IL-10 in thyroid cancer tissues were significantly correlated to extrathyroidal invasion and larger tumor size." (PMID 32655554, 2020). "Cunha and colleagues found that IL-10 expression positively correlated with extra-thyroidal invasion and larger thyroid tumor size, suggesting a role in thyroid carcinoma progression and aggressiveness." (PMID 33986723, 2020). "An autocrine production of IL-4 and IL-10 has also been reported in thyroid carcinoma cells, promoting resistance to Fas-induced apoptosis through the activation of JAK/STAT pathways." (PMID 25793261, 2015). "In addition, tumor cells can also produce cytokines including IL-10, allowing thyroid cancer cells to escape the clearance of CTL." (PMID 40075642, 2025). "IL-10 is expressed in thyroid cancer and influence the aggressiveness of it." (PMID 32655554, 2020). "Besides, higher expression of IL-10 in cancer tissues and IL-17 in serum are related to shorter recurrence-free survival of thyroid cancer patients." (PMID 32655554, 2020). "The immunosuppressive effect of IL-10 may be involved in the immune escape of thyroid cancer cells and promote the aggressiveness of thyroid cancer." (PMID 32655554, 2020). "Autocrine of IL-4 and IL-10 in thyroid cancer results in resistance to CD95-mediated apoptosis." (PMID 32655554, 2020). "Besides, autocrine production of IL-4 and IL-10 induces the over-expression of Bcl-xL and Bcl-2, two anti-apoptotic proteins, which subsequently protect thyroid cancer cells from the cytotoxic effects of antineoplastic drugs." (PMID 32655554, 2020). "Moreover, IL-4 and IL-10 have been found to increase the resistance of thyroid cancer cells to chemotherapy through the up-regulation of anti-apoptotic proteins like Bcl-2 (B cell lymphoma-2) and Bcl-xL (B cell lymphoma-extra large)." (PMID 33986723, 2020). "Autocrine secretion of IL-10 neutralizes CD95-generated signals and allows the survival and growth of thyroid cancer cells." (PMID 28099146, 2017).
Ureteral obstruction (13 papers, 2017 to 2025). Obstruction of the flow of urine through the ureter. "In addition, it has been reported that IL-10 deficiency exacerbates renal inflammation and fibrosis after ureteral obstruction in mice." (PMID 36142626, 2022). "EVs extracted from bone marrow-derived MSCs showed an increase in IL-10 with attenuation of macrophages as well as IL-6 in a ureteric obstruction model." (PMID 40535418, 2025). "This protective effect of IL-10 is demonstrated in the context of renal inflammation in the unilateral ureteral obstruction model." (PMID 28138552, 2017). "However, its role in neonatal obstructive uropathy is still unclear which led us to study the role of IL-10 in neonatal mice with unilateral ureteral obstruction (UUO)." (PMID 38448513, 2024). "After the onset of unilateral ureteral obstruction, IL-10 knockout mice show increased infiltration of inflammatory cells and cytokines, including monocyte chemoattractant protein-1, TNF-α, IL-6, IL-8, RANTES, or macrophage colony-stimulating factor, in the kidney compared with WT controls." (PMID 31194740, 2019). "Recent data show that IL-10 may display anti-fibrotic effects during unilateral ureteral obstruction through surgical ligation." (PMID 30315190, 2018). "Our in vivo findings from a murine unilateral ureteral obstruction (UUO) model of CKD showed that local deliveries of Pr-MSCs reduced collagen deposition and increased expression of the anti-inflammatory cytokine IL-10." (PMID 39234562, 2024). "We performed unilateral ureteral obstruction (UUO) in neonatal mice at day 2 of life and measured concentrations of serum IL-10 at day 7 of life by ELISA." (PMID 38448513, 2024). "Hence, we investigated their relationships with the progression of kidney fibrosis induced by ureteral obstruction and ERS in IL-10−/− mice and cultured kidney tubular epithelial cells, respectively." (PMID 36142626, 2022).
vivax malaria (13 papers, 2011 to 2022). "The aim of this study was to evaluate whether polymorphisms in the TNFA, IFNG and IL10 genes would alter the levels of anti-PvAMA1, PvDBP and -PvMSP-119 IgG antibodies in patients with vivax malaria." (PMID 27435973, 2016). "Patients with severe vivax malaria have been shown to present unbalanced concentrations of IL-10 against levels of proinflammatory biomarkers, when compared to individuals with uncomplicated vivax malaria." (PMID 31233500, 2019). "Concomitantly, it seems to be a consensus that P. vivax infection induces higher levels of IL-10 during acute phase of vivax malaria and that the cytokine levels were restored to baseline after treatment." (PMID 28118834, 2017). "Because IL-10 regulates the production and function of inflammatory cytokines, we computed IL-10/TNF-α, IL-10/IFN-γ and IL-10/IL-6 ratios and found a bias toward regulatory cytokines in clinical vivax malaria." (PMID 22973442, 2012). "In addition, these individuals with uncomplicated or asymptomatic P. vivax infections have been shown to express relatively augmented concentrations of IL-10 when compared to those with symptomatic or severe vivax malaria." (PMID 31233500, 2019). "The significance of IL-6 and IL-10 has been highlighted during vivax malaria." (PMID 28118834, 2017). "However, this was the first Brazilian study to examine this set of SNPs (IFNG-183G > T, +874A > T; TNFA −238G > A, −308G > A and −1031T > C; IL10-592C > A, −819C > T) in control cases of vivax malaria." (PMID 27435973, 2016). "Furthermore, ANXA1 may be contributing to IL-10 production in plasma of patients with vivax malaria." (PMID 24359168, 2013). "Furthermore, annexin-A1 may be contributing to IL-10 release in plasma of patients with vivax malaria." (PMID 24359168, 2013). "Furthermore, we showed that the predominantly anti-inflammatory cytokine response in clinical vivax malaria was short-lived, with IL-10 concentrations and IL-10/TNF-α, IL-10/IFN-γ and IL-10/IL-6 ratios all returning to within the normal range found in non-infected controls after chemotherapy." (PMID 22973442, 2012). "Asymptomatic vivax malaria patients presented a similar number of variables with significant concentrations increases (mainly IFN-γ, IL-10 and direct bilirubin) and decreases (such as CXCL10, IL-1β, IL-4 and indirect bilirubin)." (PMID 31233500, 2019). "When compared to symptomatic vivax malaria patients, coinfected individuals presented elevated levels of IFN-γ, IL-10 and CCL2, and diminished plasma concentrations of multiple variables as TNF-α, IL-6, IL-12, and CRP." (PMID 31233500, 2019). "It was observed that TNF-α, IL-10, ICAM-1 and VCAM-1 were the 4 best individual predictors of complicated vivax malaria with AUROC of 0.89 (95% CI: 0.84 - 0.94), 0.79 (95%CI: 0.73- to 0.86), 0.63 (0.55-0.71) and 0.84 (95% CI: 0.78- 0.90) respectively." (PMID 24324686, 2013). "IFN-γ/IL-10 ratio and CRP values marked the immune biosignature of vivax malaria patients, and could distinguish subjects with elevated creatinine levels who did not survive from those who did." (PMID 29596409, 2018). "Median concentrations of IL-6 and IL-10 were higher in severe and non-severe vivax malaria compared to controls." (PMID 25569250, 2015). "Therefore, anti-inflammatory cytokine levels may correlate either positively (IL-10; ) or negatively (TGF-β) to parasite density in uncomplicated but symptomatic vivax malaria." (PMID 22973442, 2012). "Furthermore, only symptomatic vivax malaria patients could not be distinguished from uninfected controls by their IL-10 levels." (PMID 31233500, 2019).
autoimmune myocarditis (12 papers, 2010 to 2024). Autoimmune myocarditis is an autoimmune disease that affects the heart. "High serum levels of IL-10 alongside TNF-α have previously been seen in patients with autoimmune myocarditis, but links between elevated TNF-α and pericarditis or pericardial effusions have not been observed." (PMID 38706610, 2024). "Because IL-10 was reported to have a therapeutic effect against autoimmune myocarditis, we investigated the expression of IL-10 in the hearts of EAM rats." (PMID 27501378, 2016). "In this study, we investigated an in vivo application of IL-10–overexpressing monocytes/macrophages for anti-inflammatory therapy in a murine model of autoimmune myocarditis." (PMID 23316321, 2012). "This study represents the proof of principle for a novel anti-inflammatory therapy using overexpression of IL-10 in murine monocytes/macrophages by mRNA-nucleofection for the treatment of autoimmune myocarditis." (PMID 23316321, 2012). "Autoimmune myocarditis was induced in A/J mice by subcutaneous immunization with troponin I. CD11b+ monocytes/macrophages were isolated from the peritoneum and IL-10 was overexpressed by mRNA-nucleofection." (PMID 23316321, 2012). "Application of IL-10–overexpressing CD11b+ monocytes/macrophages reduced inflammation and improved physical performance in a murine model of autoimmune myocarditis." (PMID 23316321, 2012). "IL-10 has been shown to suppress autoimmune myocarditis, and hence decreasing this cytokine in c-FLIPS mice may promote pathogenesis." (PMID 24816846, 2014). "Furthermore, we demonstrated that the application of these IL-10–overexpressing monocytes/macrophages decreased inflammation and improved physical performance in a murine model of autoimmune myocarditis." (PMID 23316321, 2012). "The cardioprotective role of IL-10 is evident by its ability to reduce proinflammatory cytokines, such as IFN-γ, TNF-α, and IL-2, in experimental autoimmune myocarditis." (PMID 23853610, 2013). "Apigenin treatment ameliorated experimental autoimmune myocarditis in BALB/c mice by modulating TH1/TH2 balance through downregulation of TH1 cytokines (TNF-α, IL-2, and interferon γ) and up-regulation of TH2 cytokines (IL-4, IL-10)." (PMID 33967832, 2021). "Overexpression of interleukin-10 (IL-10) in murine CD11b+ monocytes/macrophages via GMP-adapted mRNA-nucleofection was expected to improve clinical outcome and reduce adverse side effects in autoimmune myocarditis." (PMID 23316321, 2012).
dry eye (12 papers, 2012 to 2025). "In this study, we selected several inflammatory cytokines associated with dry eye, including IL-17A, IL-10, IL-12p70, INF-γ, IL-6, and TNF-α." (PMID 34659636, 2021). "The results showed that the Excess syndrome was associated with dizzy and spider nevus, and the Deficiency syndrome was associated with dry eyes, aversion to cold, IL-10-819C/T, and −1082A/G loci." (PMID 22690243, 2012). "The binary logistic regression analysis showed that the Deficiency syndrome was associated with dry eyes, aversion to cold, IL-10-819C/T and IL-10-1082A/G locus, and OR value at IL-10-819C/T was 4.022." (PMID 22690243, 2012). "The anti-inflammatory cytokine IL-10 exhibited a noticeable difference in the initial values between the two eyes, correlating with the severity of dry eye symptoms (the RE, which presented with more pronounced dry eye symptoms, showed higher initial IL-10 levels)." (PMID 40362547, 2025). "There were statistically significant differences in the IL‐10, IL‐35, and TGF‐β1 levels between the DED model group and the normal group (p < 0.0001), indicating that the dry eye model was successfully constructed." (PMID 39985258, 2025). "Our LPA analysis found that IL-6 and IL-8 were higher in subgroup 1 that had more severe dry eye signs, while IL-10, IL-17A, and IFN-γ were higher in subgroup 2 that had less severe dry eye signs." (PMID 38177232, 2024). "Significant differences in the concentration of cytokines (IL-6, IL-10, and TNF-α) were detected in tear samples collected from patients with dry eyes." (PMID 34659636, 2021). "Inflammatory cytokines, like type I and type II interferons and IL-6, IL-1, and TNF-α as well as immunomodulatory cytokines like IL-10 and transforming growth factor β (TGF-β), have been identified as important players in SLE and are present in the tear of dry eye patients." (PMID 25893112, 2015). "The IL‐10 level in the SF@CP@Gel treatment group was 5.01 times greater than that in the dry eye model without drug treatment group (p < 0.001), and there were significant differences between the SF@CP treatment group and the SF@CP@Gel treatment group (p < 0.05)." (PMID 39985258, 2025). "The non-SS dry eye group showed significant changes in IL-1b, IL-10, and TNF-a, but not IL-8." (PMID 39408709, 2024). "IL-1α, TNF-α and Il-10 were not modified by dry-eye condition in comparison with the basal level." (PMID 34959420, 2021).